KRAS (KRas proto-oncogene, GTPase)
Diseases named in the same sentence as KRAS in open-access papers (continued):
Sharing a sentence is not in itself a finding about the gene and the disease.
colorectal cancer (continued). "The effect of various KRAS mutations on overall survival may be explained by the fact that the heterogeneity of the various KRAS mutations in colorectal cancer may differ in carcinogenic potential." (PMID 23761841, 2013). "A better understanding of the mechanisms underlying changes in KRAS in response to epidermal growth factor receptor (EGFR) inhibitors might contribute to improvement in the treatment of colorectal cancer (CRC)." (PMID 24304820, 2013). "Regarding the three newly identified miRNA candidates, as of now miR-127-3p has been described as up-regulated in a subtype of acute myeloid leukemia and colorectal cancer with KRAS mutations and decreased in osteosarcoma cell lines and in primary breast cancer tissue." (PMID 24194846, 2013). "require KRAS mutational analysis on colorectal cancer prior to anti-EGFR therapy." (PMID 23536897, 2013). "Colorectal cancer patients with low abundance of KRAS mutation might benefit from EGFR antibody therapy and further research is needed on a larger number patients." (PMID 23874486, 2013). "In summary, our study showed that PNA-PCR method could easily detect the percentage of KRAS mutation in tumor cells and colorectal cancer patients with low abundance of KRAS mutation might benefit from EGFR antibody therapy." (PMID 23874486, 2013). "In humans, serrated colorectal cancers are associated with either BRAF or KRAS mutations." (PMID 23845441, 2013). "We proved that PNA-PCR assay could calculate the abundance of KRAS mutation and the percentage of mutant DNA in tumor cells varied a lot (10.8%∼98.3%) on the 47 colorectal cancer patients." (PMID 23874486, 2013). "Several studies suggest that cellular effects of VDR may be associated with MAPK signaling pathways, especially KRAS mutation in several cancer types such as breast and colorectal cancers." (PMID 23691496, 2013). "KRAS mutations, by contrast, occur more often in colorectal cancers that harbor chromosomal instability, the more common pattern of genomic aberrations in sporadic colorectal cancer." (PMID 24066160, 2013). "However, the possibility of two or more mutations in the same codon of the KRAS gene has seldom been reported in colorectal cancer and the real clinical impact of multiple mutations on patient prognosis has not yet been well studied and clarified." (PMID 23761841, 2013). "KRAS mutations are reported in approximately 40%–60% of all colorectal cancer specimens." (PMID 23437064, 2013). "We firstly established a PNA-PCR method which could calculate the percentage of KRAS mutation in total DNA and proved its ability on 47 colorectal cancer samples bearing KRAS mutations." (PMID 23874486, 2013). "In particular we used CCRF-CEM cell line as reference for KRAS mutation p.G12D (heterozygous), the human colorectal carcinoma cell line SW620 (used as reference for KRAS mutation pG12V, homozygous), and the human melanoma cell lines A375 (used as the source of homozygous BRAF V600E DNA)." (PMID 23536897, 2013). "Patient-derived colorectal cancer explants’ KRAS and BRAF mutation status." (PMID 22675560, 2012). "Also, cetuximab (Erbitux) and panitumumab (Vectibix) have benefited from KRAS companion diagnostic test predictive for efficacy in colorectal cancer patients and KRAS testing became mandatory for certain EGFR-kinase-targeted therapies." (PMID 23087645, 2012). "In this study, we analyzed the expression pattern of Abi1 in colonic mucosa with and without inflammation, in colonic precursor lesions, colorectal carcinoma and colorectal cancer metastasis and correlated Abi1 expression with the respective KRAS/BRAF mutation status of each lesion." (PMID 22808230, 2012). "Colorectal cancer has the second highest prevalence of KRAS mutations and understanding the factors that regulate KRAS expression may lead to future effective therapeutic strategy." (PMID 23202889, 2012). "Point mutations in codon 12 are the most common KRAS mutation in colorectal cancer." (PMID 23202889, 2012).
colorectal cancer (continued). "However, of the four patients with the G12V mutation, which is considered the most aggressive KRAS alteration in colorectal cancer, only one showed a partial response." (PMID 22569004, 2012). "Additionally, KRAS mutations in colorectal cancer lead to resistance to select treatment strategies." (PMID 23202889, 2012). "Since only 30%–50% of colorectal cancers have KRAS mutations, there has been speculation that the detection of KRAS mutation may portend a worse prognosis." (PMID 23202889, 2012). "In contrast to the classical adenoma–carcinoma sequence, deregulation of the Wnt/beta-catenin pathway is rarely observed, whereas mutations of BRAF, and less frequently KRAS have been shown to be the initiating events in the serrated route to colorectal cancer." (PMID 23045412, 2012). "Furthermore, the exposition of wild type colorectal cancer cell lines to low levels of glucose contributes to the development of mutations in KRAS, which give rise, instead, to the upregulation of GLUT1 and to an increase in glucose uptake." (PMID 20706540, 2010). "Since KLF5 has been shown to mediate the function of both APC and RAS, and mutations in APC and KRAS are common events in colorectal cancer, we examined the role of KLF5 in mediating intestinal tumor formation in mice compound for ApcMin and intestine-specific KRASV12 mutations in the current study." (PMID 20298593, 2010). "Among a cohort of 61 sporadic colorectal cancer specimens we found that 4/33 (12.1%) specimens harboring KRAS mutations were incorrectly classified as KRAS-WT using regular (conventional) PCR melting curve analysis and Sanger sequencing, despite dissection of samples for tumor enrichment." (PMID 21110880, 2010). "However, ours is the first in which to show a critical role of Klf5 in mediating the tumorigenic effect of combined Apc and KRAS mutations, a commonly encountered scenario in colorectal cancer in humans." (PMID 20298593, 2010). "To establish the critical denaturation temperature (Tc) for COLD-PCR melting curve analysis we selected a G12C KRAS-mutant FFPE colorectal cancer specimen with ~10% mutant allele based on a visual estimate of tumor nuclei and the mutant/WT melting peak height ratio using regular PCR." (PMID 21110880, 2010). "KRAS mutations were identified in 53/136 (39%) colorectal cancers." (PMID 19832985, 2009). "KRAS mutations in colorectal cancer primary tumors predict resistance to anti-Epidermal Growth Factor Receptor (EGFR) monoclonal antibody therapy in patients with metastatic colorectal cancer, and thus represent a true indicator of EGFR pathway activation status." (PMID 20020061, 2009). "HCT116, a colon cancer line that harbors a KRASG13D mutation and IPC298, a cutaneous melanoma cell line bearing an NRASQ61L mutation, were chosen for this study since KRAS in colorectal cancer and NRAS in melanoma is the most frequently mutated RAS gene in these tumor types." (PMID 19492075, 2009). "Concurrent KRAS mutations were identified in three tumors; two colorectal cancers harbored Gly12Asp/Gly13Asp and Gly12Cys/Gly13Asp and a third tumor carried Gly12Cys/Gly12Asp in an adenomatous component and additionally acquired Gly12Val in the invasive component." (PMID 19832985, 2009). "Interestingly, BRAF mutations are mutually exclusive with NRAS mutations in melanoma and KRAS mutations in colorectal cancer." (PMID 19492075, 2009). "The specific KRAS mutation may thereby influence different aspects of tumor progression, which could explain why repeated KRAS targeting is observed in a subset of colorectal cancer." (PMID 19832985, 2009). "Moreover, these metabolic changes observed in G12D and G12V SW48 cells show striking similarities to the consensus molecular subtype 3 (CMS3) of colorectal cancer types, which show an association between increased KRAS mutations and elevated metabolic signature of glutamine and nitrogen metabolism." (PMID 41266617, 2026).
colorectal cancer (continued). "However, the KRAS associated neoantigens, which have been widely documented in the literature to be genuinely present in colorectal cancer, could demonstrate the reliability of our methodology to some extent." (PMID 40515555, 2025). "Notably, the G13D mutation is present in 25% of colorectal cancers driven by KRAS." (PMID 40244134, 2025). "This review concentrates on KRAS-driven oncogenic transformation, as KRAS mutations are among the most common in human cancers, accounting for over 90% of pancreatic ductal adenocarcinoma cases, around 30% of lung cancers, and approximately 50% of colorectal cancers." (PMID 40527836, 2025). "Moreover, vitamin C has been shown to selectively kill BRAF and KRAS-mutated colorectal cancer cells, further suggesting that low vitamin C levels may facilitate growth of BRAF-mutated tumors." (PMID 40102611, 2025). "Similarly, KRAS mutations occur in 35% to 45% of colorectal cancers." (PMID 40906088, 2025). "Notably, colorectal carcinomas with KRAS mutations display a distinct immunoregulatory profile, marked by the pronounced downregulation of immune checkpoints such as BTLA, CTLA-4, and TIGIT—a pattern in sharp contrast to that observed in pulmonary malignancies." (PMID 40303413, 2025). "In addition, compared with KRAS‐wild‐type tumors, other KRAS‐mutated tumors were also associated with a higher 5‐year colorectal cancer‐specific mortality (with univariable HR, 1.63; 95% CI, 1.27–2.09; p = 0.0001; and multivariable HR, 1.57; 95% CI, 1.22–2.02; p = 0.0004)." (PMID 39039804, 2024). "Thus osthole plays an antitumor role in colorectal cancer cells with KRAS mutations." (PMID 38738174, 2024). "This suggests that for patients with resistance to fulvestrant generated by F404 mutations, there may be the possibility of rechallenging with fulvestrant after a treatment break, as has been seen rechallenging with cetuximab in patients who KRAS mutations in colorectal cancer." (PMID 37982575, 2024). "Therefore, BCAM/laminin α5 may exert a significant role in the metastatic process of colorectal cancer cells with KRAS mutations." (PMID 39000374, 2024). "Thus, this case may also benefit from multikinase KRAS (on) inhibitors, which could have significant implications for the management of colorectal cancer where pathogenic APC mutations are enriched." (PMID 38791940, 2024). "Therefore, statins may be therapeutically useful as adjuvants to L-OHP in KRAS-mutated colorectal cancer and may also be useful in the treatment of L-OHP-induced neuropathy." (PMID 37069612, 2023). "Because clinical treatment of KRAS-mutated colorectal cancer is different from KRAS wild-type colorectal cancer, it is important to determine whether this group of colorectal cancers is associated with Fn infection that may negatively affect prognosis and the efficacy of chemotherapy." (PMID 37772997, 2023). "Notably, mutated EGFR in lung cancer and KRAS in colorectal cancer are therapeutic targets of FDA‐approved drugs, and their lower carrier rates in early‐onset cancers may restrict relevant drug applications." (PMID 37610374, 2023). "Therefore, discovering an inhibitor, such as KRB-456, which binds KRAS G12D and KRAS G12V, will have a broader impact on human cancers, particularly in PDAC, colorectal cancer, and other cancers where the incidence of KRAS G12D and KRAS G12V mutations is significant." (PMID 38051103, 2023). "Additionally, an integrative analysis of tumors demonstrated that, in comparison to primary colorectal cancer (pCRC), peritoneal metastasis (PM) features a comparable KRAS mutation rate, but with an increased incidence of GNAS (mucinous) and BRAF (non-mucinous) pathways." (PMID 37689664, 2023).
colorectal cancer (continued). "Finally, with the aim of translating these results to real clinical samples, the detection of the KRAS G12V mutation was evaluated in EVs isolated with ExoGAG technology from plasma samples of colorectal cancer (CRC) patients carrying the mutation (previously determined by Beaming technology)." (PMID 36830940, 2023). "Therefore, to further investigate the relationship between KRAS and punctate IKKα expression observed in the present study, future studies in colorectal cancer should investigate the relationship between CHUK mutations, KRAS mutations and IKKα expression in patient samples." (PMID 35173303, 2022). "Finally, a recent study from our group demonstrated that high levels of phosphorylated Y88 p27 led to increased resistance to Palbociclib, in KRAS-mutated colorectal cancer, but administration of the Src-inhibitor Saracatinib was able to restore Palbociclib sensitivity, both in vitro and in vivo." (PMID 35712501, 2022). "Furthermore, KRAS mutations are also frequently identified in colorectal cancer, suggesting that L-ASNase therapy might also be relevant in a subset of colorectal cancer patients." (PMID 35205650, 2022). "Nevertheless, this differential mutational profile suggests that IKKα signalling may be occurring through two independent mechanisms, one which is associated with AR mutation and the other which is associated with alterations in KRAS and inferior survival outcomes in primary colorectal cancer." (PMID 35173303, 2022). "Primary tumor laterality (PTL) is the most recently identified prognostic factor associated with mortality in patients with resected colorectal cancer liver metastases, but whether it is prognostic in all patients or only those with wild-type KRAS tumors is debated." (PMID 35159066, 2022). "Thus, the 177Lu-DN(C19)-CXCR4L nanosystem demonstrated a synergistic effect of chemo/radiation therapy, which could be implemented in colorectal cancer with mutated KRAS." (PMID 35631681, 2022). "In a comprehensive analysis of advanced colorectal cancer and an evaluation of the concordance rate of a few driver mutations between primary and metastatic lesions, a concordance rate of approximately 95% was found when focusing on KRAS and BRAF hot point mutations." (PMID 35274488, 2022). "In 68 patients with colorectal carcinoma (CRC), key driver mutations were detected as follows: KRAS, 40 (59%); NRAS, 1 (1%); BRAF, 4 (6%); ERBB2, 2 (3%); and ERBB3, 1 (1%)." (PMID 35323313, 2022). "In addition, it was observed that patients with PD (P = 0.034) or some types of tumor (e.g., esophageal cancer, colorectal cancer, and pancreatic cancer) (P < 0.01) and patients with colorectal cancer who had KRAS mutations (P = 0.039) were more likely to have HDP after subsequent immunotherapy." (PMID 34239621, 2021). "Interestingly, the activity of vitamin C against KRAS/BRAF mutated colorectal cancer might be useful to counteract tumor resistance to anti-epidermal growth factor receptor (EGFR) monoclonal antibodies (i.e., cetuximab, panitumumab)." (PMID 33804775, 2021). "Thus, we infer that TMEM16A protein may promote the occurrence and growth of colorectal cancer by activating mutated KRAS." (PMID 33816307, 2021). "Furthermore, it has recently been shown that pharmacologic ascorbate kills colorectal cancer cells depending on the KRAS mutational status, and it impairs the Warburg effect by resulting in the downregulation of both GLUT1- and PKM2-dependent protein expression." (PMID 33925206, 2021). "Importantly, Kaplan–Meier analysis revealed that co-occurrence of RNF43 and KRAS mutations was associated with a poorer outcome for colorectal cancer, compared to single mutations of each gene, although the samples size was not enough to obtain significant differences." (PMID 32934222, 2020).
colorectal cancer (continued). "Another assumption for KRAS mutation status heterogeneity could be DNA degradation as well the possibility that discordance is based on the existence of a secondary tumor next to the colorectal cancer entity." (PMID 33002027, 2020). "Besides, KRAS mutation in colorectal cancer has been reported and KRAS/BRAF genes mutation might make EGFR inhibitors ineffective." (PMID 31998788, 2020). "Approximately, 30%‐50% of colorectal tumors are known to have a mutated KRAS gene, predominantly found in codons 12 and 13, indicating that up to 50% of patients with colorectal cancer may respond to anti‐epidermal growth factor receptor (EGFR) antibody therapy such as cetuximab." (PMID 32329932, 2020). "The results could guide the use of liquid biopsy in KRAS mutation detection in colorectal cancer." (PMID 32590745, 2020). "Besides PC, KRAS mutations are predominant in lung and colorectal cancers." (PMID 31731578, 2019). "Thus, the development of additional PROTACs mediating the degradation of the BAF complex may provide new therapeutic approaches for KRAS-mutated colorectal cancer." (PMID 31217031, 2019). "Besides its crucial role in the tumor development, the KRAS mutational status is also critical for the antiepidermal growth factor receptor (EGFR) therapy management in colorectal cancers, which has greatly improved the clinical outcome of the disease in the past decade." (PMID 30406144, 2018). "Additionally, we showed that KRAS or BRAF mutation could be associated with improved prognosis in MSI-positive colorectal cancers." (PMID 30042065, 2018). "It has been reported that E-cadherin engagement leads to ERK inhibition in a PI3K/Akt-dependent pathway in differentiating intestinal epithelial cells, and in KRAS-mutated colorectal cancers, suggesting PLCD1 may suppress phosphorylation of ERK by engaging E-cadherin." (PMID 28423710, 2017). "While the role of KRAS gene mutations has been widely accepted for predicting responses to anti-EGFR therapy in patients with colorectal cancer, although this study was based on observation of a single case it gives hope that some KRAS gene mutation may have favorable prognosis." (PMID 28265402, 2017). "Furthermore, activating mutations in KRAS or BRAF occur in approximately 50%–60% of patients with colorectal cancer; these mutations are mutually exclusive and are associated with resistance or decreased response to anti-epidermal growth factor receptor therapy in colorectal cancer." (PMID 28152546, 2017). "Until recently, indications for standard-of-care molecular testing in colorectal carcinomas (CRC) included testing for exon 2 KRAS mutational status as a predictor of response to cetuximab (Erbitux; Merck KGaA) and to panitumumab (Vectibix; Amgen Inc.)." (PMID 28404952, 2017). "The corresponding KRAS single amino acid missense mutations are located at codons 12 or 13 for exon 2, codons 59 or 61 for exon 3, and codons 117 or 146 for exon 4, with G12D (13.1% prevalence), G12V (11.6%), and G13D (8.1%) being most prevalent in colorectal cancer." (PMID 27685259, 2016). "Thus, testing for KRAS mutations, which are found in approximately 40 % of colorectal cancers, has become routine in the management of metastatic CRC (mCRC) prior to cetuximab or panitumumab treatment and is even required by the responsible regulatory agencies." (PMID 27485514, 2016).